AR (androgen receptor)
Diseases named in the same sentence as AR in open-access papers (continued):
Sharing a sentence is not in itself a finding about the gene and the disease.
prostate carcinoma (continued). "Previous studies have reported that they have several mutations of the AR genes, which makes them resistant to ADT, a common treatment for prostate cancer." (PMID 36672609, 2022). "Prostate cancer growth is driven by androgen receptor signaling, and advanced disease is initially treatable by depleting circulating androgens." (PMID 35033184, 2022). "It has been realized that enzalutamide-resistant prostate cancer frequently assumes deadly phenotype if AR-independent mechanisms develop, though the spectrum of which is yet to be fully characterized." (PMID 34973338, 2022). "The dependence of the development of prostate cancer (PCa) on the effects of androgens and AR was first proved by Hyggins and Hodges." (PMID 35055079, 2022). "PROTAC 8 was thus expected to be developed as a promising drug candidate for AR-positive prostate cancer and a valuable tool compound to study the biological function of BRD4." (PMID 35702740, 2022). "Androgen deprivation therapy (ADT) has been developed to inhibit AR signaling and has been considered as the golden standard in treating prostate cancer." (PMID 35966880, 2022). "Evidence suggests that the expression of estrogen receptor (ER)-α and ER-β are modulated in prostate cancer and function independently of the AR." (PMID 35453603, 2022). "Prostate cancer is generally thought of as a hormone-driven disease, dependent on androgen-mediated androgen receptor (AR) signaling for growth." (PMID 36671452, 2022). "AR not only plays a key role in the maintenance of musculoskeletal and male sex-related functions but also in the progression of prostate cancer." (PMID 36536188, 2022). "Several inhibitors of androgen receptor (AR) function are approved for prostate cancer treatment, and their impact on gene transcription has been described." (PMID 36611998, 2022). "The androgen receptor (AR) is a ligand-dependent transcriptional factor and an important therapeutic target for prostate cancer." (PMID 36015192, 2022). "The relative expression value of AR is therefore demonstrated in this study as an important marker of malignant prostate neoplasms." (PMID 35456428, 2022). "ERα stimulates prostate cancer cell proliferation and promotes the development of prostate malignancy; ERβ downregulates AR signaling and acts as tumour suppressor." (PMID 35547880, 2022). "The AR is the primary therapeutic target in prostate cancer; copy number increases affecting the AR gene body and distant enhancer produce upregulation of AR expression in mCRPC after tumors escape ADT." (PMID 36251389, 2022). "Fascinatingly, targeting AR signaling is widely investigated for treatment of multiple types of cancers, especially in prostate cancer." (PMID 36013056, 2022). "An ongoing trial studying PSMA-PET in breast cancer as a biomarker of androgen resistance in HER2-negative, AR-positive breast cancer is ongoing (NCT04573231), noting such an association in prostate cancer." (PMID 35729608, 2022). "Here the authors show that AR activation in a subpopulation of prostatic progenitor cells can initiate prostatic intraepithelial neoplasia formation and promotes prostate cancer development through activation of IGF1 and Wnt/β-catenin signalling pathways." (PMID 35902588, 2022). "When ER or AR was knocked down in BC cell lines (MCF-7) or prostate cancer cell lines (LNCaP-FGC), the amounts of 5′-tRNA-Asp-GUC and 5′-tRNA-His-GUG were reduced." (PMID 36072340, 2022). "While AR and GR transcriptional output presents a considerable overlap, GR activation leads to an attenuation of AR-dependent transcriptional programs, hence a partial antiandrogen effect, suggesting the tumor suppressor role of GR in prostate cancer." (PMID 35761157, 2022). "Androgen and androgen receptor play a critical role in the occurrence and development of prostate cancer." (PMID 36015177, 2022).
prostate carcinoma (continued). "Competing roles of miRNAs and lncRNAs in regulating gene expression and an additional role of miRNAs in repressing translation in AR-independent prostate cancer and in NEPC have been reported." (PMID 35682963, 2022). "AR produces ROS, and oxidative stress evokes AR signaling and contributes to the pro-survival and anti-apoptotic effects of prostate cancer cells in response to androgen deprivation." (PMID 36551308, 2022). "Our results indicate that high prostate cancer AR activity is required for tumor regression by BAT, which occurs in part through downregulation of MYC." (PMID 36194476, 2022). "Both transcription factors play important roles in AR-directed transcription in prostate cancer but have been less investigated in benign prostate cells." (PMID 35203681, 2022). "Research conducted on a cell line derived from Caucasian human prostate carcinoma (LNCap), in a model of androgen-dependent prostate cancer, revealed that the exposure of cells to Fin for 1–6 months increased AR expression." (PMID 36359245, 2022). "Liquid biopsies in patients with prostate cancer are usually done in clinics once multiple therapies such as androgen-receptor axis targeting agents and taxanes have been utilized." (PMID 36185208, 2022). "Another experiment reveals the role of AR signaling in autophagy regulation in prostate cancer cells." (PMID 35317831, 2022). "Overall, these perturbation studies confirmed the functional importance of distinct pathways identified in AR-positive and AR-null prostate cancers." (PMID 35406510, 2022). "Both of them bind to AR and inhibit androgen-mediated gene transcription in AR-overexpressing prostate cancer cells, but also impair the nuclear localization of AR and DNA binding." (PMID 36144603, 2022). "This study describes a tumor suppressor role of microRNA miR‐30e in prostate cancer (PCa), mediated by modulation of AR signaling, cell cycle, apoptosis and ubiquitination pathways." (PMID 35612714, 2022). "In prostate cancer, the methylation of CpG islands located in the AR promoter and microRNA modulation leading to the silencing of gene transcriptional activity was reported." (PMID 35053220, 2022). "In this study, we showed that the two immunophilins, FKBP51 and FKBP52, are known to be regulators of AR and are required for prostate cancer proliferation." (PMID 34057812, 2022). "Our study identifies the SWI/SNF complex as a transcriptional dependency in AR/FOXA1-driven prostate cancer." (PMID 34937944, 2022). "The initial clinical management of metastatic prostate cancer is based on disruption of the androgen receptor (AR) signaling axis, and prior to 2015 this was achieved through the use of single agent androgen deprivation therapy (ADT)." (PMID 35304525, 2022). "HSD17B4 expression is known to increase in castration resistant prostate cancer, leading to metabolic re-programming resulting in AR-stimulation and poor prognosis." (PMID 35563746, 2022). "We applied that concept to the mutual influences of AR and NF-κB including the oncogene c-Myc, which is crucial in a high percentage of prostate cancers." (PMID 36551650, 2022). "Although significant effort has been devoted to directly targeting AR-expressing tumor cells, these therapies failed in most prostate cancer patients." (PMID 36323713, 2022). "More recent studies have shown that PAD2 also appears to facilitate androgen receptor target gene expression in prostate cancer cells via similar mechanisms." (PMID 36224627, 2022). "Other AR targeted agents now licensed for the treatment of prostate cancer include daralutamide and apalutamide." (PMID 35563176, 2022). "Although the mainstay treatment for advanced prostate cancer relies on suppression of AR activity, there is accumulating evidence that potent activation of AR by treating patients with CRPC with high doses of testosterone can also be of therapeutic benefit." (PMID 36923279, 2022).
prostate carcinoma (continued). "The complex genomic landscape of prostate cancer evolves across disease states under therapeutic pressure directed toward inhibiting androgen receptor (AR) signaling." (PMID 35943799, 2022). "Our previous study finds that NCAPD3 is an androgen/androgen receptor (AR) axis-targeted gene and is involved in AR-promoted progression of prostate cancer." (PMID 35689245, 2022). "For example, in prostate cancer, miR-17 has been demonstrated to attenuate androgen receptor signaling and cell growth by targeting proto-oncogenic transcriptional activator PCAF." (PMID 35536524, 2022). "Prostate cancer cells with resistance to enzalutamide display chromatin reprograming and modifications in AR and Myc binding compared to sensitive cells." (PMID 35682963, 2022). "AR signaling plays a key role in normal prostate development as well as in prostate cancer pathogenesis." (PMID 36212399, 2022). "In the context of AR signaling, GR competes with AR for DNA-binding and has the potential to halt the proliferation rate of prostate cancer cells." (PMID 35866830, 2022). "In prostate cancer cells, androgen receptor (AR) translation is regulated by DDX3, which impacts castration-resistance in this cancer type." (PMID 36393867, 2022). "They showed that direct interaction of ARD1 with AR facilitated the binding of the AR to its targeted gene promoters and demonstrated that ARD-1 dependent acetylation of the AR enhances AR-mediated gene transcription and tumorigenesis of prostate cancer cells." (PMID 36060957, 2022). "This mild effect was directly sought for the use of the drugs in the repression of the AR-promoted/sustained prostatic cancer." (PMID 36233256, 2022). "This is analogous to the prior observation that FOXA1 binds to the androgen receptor enhancer and regulates its expression in prostate cancer cells." (PMID 35703180, 2022). "Arrest-defect-1 protein (ARD1) is an acetyltransferase that forms a complex with AR and Hsp90, leading to AR acetylation, resulting in AR nuclear translocation, AR target gene expression, and prostate cancer tumorigenesis." (PMID 36551557, 2022). "As expected, silencing TR3 decreased the protein and mRNA levels of AR and AR-Vs in AR-positive prostate cancer cells." (PMID 35454821, 2022). "Androgens and androgen receptor play a critical role in prostate cancer oncogenesis, and ADT has traditionally been an essential first-line treatment for PCa." (PMID 36439479, 2022). "For example, the transcriptional activity of androgen receptor (AR), which drives prostate cancer, is inhibited upon modification of this protein by SUMO1 near its N-terminus." (PMID 35269436, 2022). "Taken together, analyses identified a new mechanism for IGF1R and AR stimulation of prostate cancer, and further support the relevance of targeting AR and IGF1R in this type of tumors with BRCA1 serving as a marker for defining the target activity." (PMID 35432218, 2022). "We detected a higher level of TMPRSS2 in the tumors, presumably because the activated AR in prostate cancer directly bind to its promoter region." (PMID 36088396, 2022). "In prostate cancer, AR plays a pivotal role in the regulation of tumorigenesis and tumor progression." (PMID 35233061, 2022). "RNA-seq analysis revealed that many of the prostate cancer related gene products regulated by metformin within the C4–2 cell line are also AR target genes." (PMID 36175875, 2022). "Androgen receptor alterations have been identified as some of the main drivers of castration-resistant prostate cancer." (PMID 35053623, 2022). "Almost all primary prostate cancer cells express the AR and are dependent on androgens for their oncogenic growth and survival." (PMID 35902588, 2022).
prostate carcinoma (continued). "In this line of thought, increased prostate cancer incidence and mortality in Black versus White men were speculatively attributed to higher levels of circulating sex steroids, to differences in AR structure and function, or to both differences in hormone levels and ancestry-associated AR variants." (PMID 35104804, 2022). "It was reported that each ING1b and ING2a functions as corepressor of AR in prostate cancer cells, cross-talk and compensate their activity if one is downregulated." (PMID 36056353, 2022). "The epigenetic and chromatin regulators CHD1, SWI/SNF, and EZH2 likewise play important roles in the evolution of the AR cistrome and prostate cancer biology." (PMID 36212399, 2022). "In prostate cancer, AR is reported to suppress prostate cancer cell EMT by regulation of AKT signaling pathway." (PMID 35605663, 2022). "This situation results from the overexpression of AR, which has been confirmed in patients with prostate cancer who develop tumor progression at the time of using ADT (androgen deprivation therapy)." (PMID 35055079, 2022). "USP14 is often overexpressed in tumours and has been shown to deubiquitinate and stabilise the androgen receptor in models of breast and prostate cancer." (PMID 36240066, 2022). "Prostate cancer onset and progression are closely correlated with the androgen receptor (AR) activity The activation of AR is mediated by androgens, whose synthesis is regulated by the hypothalamic–pituitary–testicular (HPT) axis." (PMID 35864113, 2022). "As PI3K/Akt signaling is highly active in AR-prostate cancer, RL91 was used in combination with raloxifene in in vitro studies." (PMID 35453603, 2022). "Previously, we have demonstrated that increased eNOS expression and NO production can contribute to antiandrogen-resistant growth of prostate cancer cells via a mechanism of suppression of AR transactivation and also activation of protein kinase Akt." (PMID 35526071, 2022). "TR3 alters AR expression, splicing process, and activity in prostate cancer cells, increasing the androgen independence of AR signaling." (PMID 35454821, 2022). "Here the authors show that inhibition of the androgen receptor pathway leads to the upregulation of CS, which promotes prostate cancer growth and metastasis." (PMID 35963852, 2022). "AR-mediated metabolic reprogramming promotes proliferation of prostate cancer cells by positively regulating anabolic metabolism and lipogenesis." (PMID 35708495, 2022). "This contrasts the findings of Pomerantz and colleagues, where they observe a clear distinction between the AR cistromes of primary prostate cancer and mCRPC patient samples." (PMID 36212399, 2022). "During prostate cancer development and progression, the AR cistrome undergoes systematic changes, accessing certain gene expression programs while abandoning others." (PMID 35509021, 2022). "Functional interactions between AR and the β-catenin pathway were previously characterized in prostate cancer." (PMID 35372424, 2022). "A previous study showed that OCT1, an androgen receptor (AR) collaborative factor, can coordinate AR signaling to promote the growth of prostate cancer." (PMID 36497375, 2022). "In prostate cancer cells, GR and androgen receptor (AR) share overlapping transcriptomes and cistromes." (PMID 35866830, 2022). "Due to this critical role of AR signaling in driving prostate cancer, therapy targeting the AR pathway has been the mainstay strategy for metastatic prostate cancer treatment." (PMID 35864113, 2022). "Mechanistic studies reveal that SOX9 regulates Androgen Receptor (AR) expression, drives the WNT signaling pathway activation in prostate cancer, and is associated with endocrine resistance in breast cancer." (PMID 36230806, 2022). "SFN interfered with heat shock protein 90 (Hsp90), a critical androgen receptor (AR) chaperone, in prostate cancer." (PMID 36139145, 2022).
prostate carcinoma (continued). "There is evidence showing that RORγ was upregulated in metastatic castrate-resistant prostate cancer and promoted the expression of the androgen receptor, thus raising the possibility of targeting RORγ for cancer treatment." (PMID 35246220, 2022). "Acetylation of Hsp90 is regulated by cytoplasmic HDACs such as HDAC6, while Hsp90 regulates AR activity and stability in prostate cancers." (PMID 35582529, 2022). "Among the multiple AR-Vs reported, AR-V7 (AR3) is the most common in prostate cancer cell lines and tumors and is generated by splicing between exon 3 and cryptic exon 3 (CE3) as well as exon 3 duplication." (PMID 35454821, 2022). "The goal of the current study was to examine the signaling pathways regulated by metformin in AR positive, castration-resistant prostate cancers." (PMID 36175875, 2022). "Bicalutamide is a second-generation AR antagonist that is designed to prevent androgens from binding to AR and is widely used in prostate cancer patients." (PMID 36376959, 2022). "Elevated carboxypeptidase-D played an anti-apoptotic activity in prostate cancer, which is inhibited by combined prolactin receptor and androgen receptor targeting." (PMID 35686102, 2022). "This indicates that AR abundance and activity is a major determinant of prostate cancer response to SPA in vitro." (PMID 36194476, 2022). "While AR drives prostatic carcinogenesis, ZFHX3 is a tumour suppressor whose loss activates the PI3K/AKT signalling in advanced prostate cancer (PCa)." (PMID 34953044, 2022). "TRIM24 promotes prostate cancer proliferation at low androgen conditions and bolsters androgen receptor signaling." (PMID 35105347, 2022). "ChIP-Seq analysis of prostate cancer cell lines revealed AR peaks in several genes involved in lipid synthesis." (PMID 35682963, 2022). "Intracellular delivery of miRNA-124 reduces AR splice variants and suppresses EZH2 as a downstream target to prevent prostate cancer progression." (PMID 35236381, 2022). "Together, our study indicates that EGFR pathway is inhibited by GDF15 in untreated and short-term AR inhibitor treated LNCaP prostate cancer cells." (PMID 35853851, 2022). "Further investigation reveals that AR-mediated autophagy induction is vital for proliferation and viability of prostate cancer cells and is correlated with poor prognosis." (PMID 35317831, 2022). "Another study targeting AR signaling comprised the combination treatment of androgen-accustomed DuCaP-N prostate cancer cells with the HDAC inhibitor TSA, the anti-androgen bicalutamide, and the 5α-reductase inhibitor finasteride." (PMID 35582529, 2022). "As a result of the indispensable role of AR in prostate cancer, a number of anti-AR drugs have been developed and approved for different stages of prostate cancer in the past 30 years." (PMID 35864113, 2022). "Using public published big data, we found that the expression of succinylation-related gene Glycine-N-acyltransferase-like 1 (GLYATL1) and prostate cancer-related gene (AR) in 498 PCa tissues were significantly higher than that in non-cancer tissues." (PMID 36387072, 2022). "To evaluate these findings, we collected mRNA from luciferase or CREB5-overexpressing prostate cancer cells, including the AR-dependent LNCaP and LAPC-4 cells, as well as the AR-negative PC3 and DU145 cells." (PMID 35550030, 2022). "A novel peptide PROTAC targeting androgen receptor DNA binding domain via AI‐Rosetta assisted design for castration‐resistant prostate cancer therapy is presented." (PMID 35971165, 2022). "Previous studies have found that AR is an important downstream molecule of the MAPK/ERK signaling pathway in prostate cancer." (PMID 36261201, 2022). "The present study is the first to demonstrate that TR3 affects the AR splicing process as well as its expression and further enhances androgen-independent AR activity in prostate cancer cells." (PMID 35454821, 2022).